STAT3 (signal transducer and activator of transcription 3)
Diseases named in the same sentence as STAT3 in open-access papers (continued):
Sharing a sentence is not in itself a finding about the gene and the disease.
osteosarcoma (continued). "Several key oncogenic genes and pathways have been identified in OS, including the NOTCH, WNT/beta-catenin, and JAK/STAT3 signaling pathways as well as the transcription factors RUNX2 and Osterix, while the molecular mechanisms of osteosarcoma genesis and progression remained poorly understood." (PMID 34168981, 2021). "The exosomal PYK2 activates RhoA in its negative recipient osteosarcoma cells and induces signal transducer and activator of transcription 3 activation in its recipient macrophages to increase M2 phenotype." (PMID 33568623, 2021). "The lncRNA NEAT1/miR-483/STAT3 axis regulated the EMT and metastasis of osteosarcoma cells, which might represent new drug targets for the treatment of osteosarcoma in the future." (PMID 33546665, 2021). "Thus, a low STAT3/STAT1 ratio indicated the impaired migration, invasion and EMT of osteosarcoma cells, consistent with a previous report describing the correlation between STAT3/STAT1 ratio and patient survival." (PMID 33546665, 2021). "In osteosarcoma, apatinib exerted its antitumor effects via VEGFR2/STAT3/BCL-2 pathway." (PMID 34429133, 2021). "In osteosarcoma cells, curcumin was able to reduce growth viability and survival in addition to blocking the cell cycle progression of the G2/M phase as a result of JAK2/STAT3 inhibition." (PMID 32731620, 2020). "In both cell lines, phosphorylated JAK2 and STAT3 was decreased while phosphatase SHP1, a negative regulator of STAT3, was upregulated, indicating that BD reversed the constitutive activation of the JAK2/STAT3 signaling pathway in the osteosarcoma cell lines." (PMID 36046775, 2020). "The inhibitory effects of ML264 on osteosarcoma cells are likely mediated via inhibition of JAK2 and STAT3 phosphorylation, decrease in β‐catenin and Runx2 levels, down‐regulation of cyclin D1, cyclin E1, CDK4, N‐cadherin, vimentin, Snail and MMPs expression, and up‐regulation of E‐cadherin levels." (PMID 32285603, 2020). "Interestingly, the up-regulation of COX-2 was accompanied by STAT3 phosphorylation and facilitation of epithelial-mesenchymal transition (EMT), which resulted in osteosarcoma metastasis and invasion." (PMID 32171274, 2020). "In addition, irisin inhibits the proliferation, migration, and invasion of osteosarcoma cells and reverses the IL-6 induced EMT in osteosarcoma cells via the STAT3–Snail signaling pathway." (PMID 30323244, 2018). "Also, siRNA-mediated inhibition of STAT3 leads to the downregulation of survivin and VEGF-A in canine osteosarcoma cells." (PMID 30286779, 2018). "Thus, we sought to identify the link between STAT3 activation by ADSCs in the TME and the osteosarcoma-promoting effects of ADSCs." (PMID 28423603, 2017). "Therefore, we suggest that the inactivation of the Src-Stat3 pathway by AMBN, combined with conventional doxorubicin treatment, can be a therapeutic modality for osteosarcoma." (PMID 28054649, 2017). "Our results also suggest that STAT3 and ERK1 inhibitors might be used in combination with common chemotherapeutic drugs in osteosarcoma in order to increase the response to chemotherapy and to improve the prognosis." (PMID 25146150, 2014). "Recent studies on osteosarcoma involving the LCP1 gene (also known as actin-bundling protein L-plastin or LPL), have shown that the aberrant expression of LCP1 gene activates the JAK2/STAT3 signaling pathway, linking IL-6, IL-6R, and LCP1 in the context of tumor progression." (PMID 40759647, 2025). "Furthermore, exosomal PYK2 activates RhoA in receptor-negative osteosarcoma cells and triggers STAT3 in receptor-positive macrophages, promoting the M2 macrophage phenotype." (PMID 39068459, 2024).
osteosarcoma (continued). "Additionally, co-administration of TGT with EGFR inhibitors, STAT3 inhibitors, and VEGFA inhibitors may enhance the anti-osteosarcoma effects of TGT, further inhibiting the development and metastasis of osteosarcoma." (PMID 38297292, 2024). "Furthermore, genetic inhibition of STAT3 prevented osteosarcoma 143.98.2 xenograft growth in vivo, suggesting that targeting JAK/STAT3 may be a promising therapeutic strategy for osteosarcoma patients." (PMID 36923933, 2023). "Experimental results showed that luteolin could inhibit cell viability and significantly decrease the expression of AKT1, STAT3, IL6, TNF, and VEGFA, and luteolin could also inhibit osteosarcoma proliferation and metastasis in osteosarcoma orthotopic mouse model." (PMID 37749554, 2023). "However, it is unclear on the relationship between JAK2/STAT3 pathway and FANCD2 in osteosarcoma." (PMID 36814203, 2023). "Besides the STAT3-EMT and PI3K/AKT-FOXO1 signaling pathways, we found that new signals including CD44 and CXCL8 were also involved in DS−1-induced physiological regulation in human osteosarcoma U−2 OS cells." (PMID 35744840, 2022). "Furthermore, we showed that low expression of TIPE1 was related to advanced-stages of osteosarcoma and that the expression of TIPE1 had a negative relationship with the expression of STAT3 in osteosarcoma patients." (PMID 36151091, 2022). "Thus, treatments targeting STAT3 may represent one promising approach to block the EMT and metastasis of osteosarcoma cells." (PMID 33546665, 2021). "Therefore, blocking of STAT3 signaling by AG490, a JAK2 inhibitor, or the knockdown of IL-6 using siRNA could re-sensitized drug-resistant osteosarcoma cells to doxorubicin and cisplatin." (PMID 34198693, 2021). "Thus, other signaling pathways could be activated in osteosarcoma cells and counterbalance cell cycle inhibition observed in the presence of ICG-001, such as activation of cyclin D1 gene transcription by Jun/Fos or STAT3 factors." (PMID 34062831, 2021). "Besides STAT3/c-Myc signaling pathway, various signaling pathways, including RANKL (receptor activator of nuclear factor-κB ligand)/ RANK (receptor activator of nuclear factor-κB) and Wnt signalings, were also involved in the tumorigenesis of osteosarcoma." (PMID 34922636, 2021). "A response of osteocytes to IL-11 has not been reported previously, but IL-11 stimulates STAT3 phosphorylation in primary calvarial osteoblasts, and we have observed downregulation of sclerostin by IL-11 in an osteosarcoma-derived cell line (UMR106-01, Patricia W.M. Ho, unpublished data)." (PMID 32458800, 2020). "Therefore, preventing STAT3 phosphorylation is an enticing strategy to defeat resistance to EGFR inhibitors such as erlotinib in various tumor types, including relapsed or refractory osteosarcoma." (PMID 31422383, 2019). "We investigated the direct action of a small molecule inhibitor of STAT3 (LLL12) in human umbilical cord vascular endothelial cells (HUVECs) in vitro, in a Matrigel model for angiogenesis in vivo, and its antitumor activity in a xenograft model of osteosarcoma." (PMID 22530037, 2012). "Further, it is also not clear what role of Stat3 may play in cell growth and survival in human sarcoma cells, including osteosarcoma and rhabdomyosarcoma cells." (PMID 17598902, 2007). "Additionally, different signaling pathways such as STAT3/c‐Myc signal pathway, JNK signl pathway, PI3k/AKT/mTOR signal pathway, WNT/β‐catenin signal pathway, and RhoA signal pathway can influence the development of osteosarcoma by regulating PCD in osteosarcoma cell." (PMID 38800967, 2024). "Finally, TNFα-induced protein 8-like protein 1 (TIPE1) inhibits osteosarcoma carcinogenesis and metastatic activity by binding to and inhibiting PRMT1 which is required for the asymmetric dimethylation of STAT3 on R688 (STAT3R688me2a), a modification that stimulates the activity of STAT3 itself." (PMID 39680066, 2024).
osteosarcoma (continued). "Furthermore, EMT inactivation inhibited proliferation, migration, invasion, and in osteosarcoma by targeting zinc finger E-box-binding protein 1 (ZEB1) through inactivation of c-Jun N-terminal kinase (JNK) and JAK1/signal transducer and activator of transcription 3 (STAT3) pathways." (PMID 33472642, 2021). "Consequently, ADSCs in adipose tissue may increase osteosarcoma cell proliferation and metastasis in conjunction with changes in MMP2/9 and E-cadherin expression, which are at least partially mediated by the activation of the STAT3 signalling pathway." (PMID 28423603, 2017). "Acute high glucose (30 mM) exposures increased STAT3 activation and XRCC1 protein and gene expression in the non-tumorigenic HEK293T and osteosarcoma U2OS cell lines." (PMID 35457130, 2022). "L48H37 can reduce the phosphorylation of STAT3, JAK1, JAK2, and JAK3 in osteosarcoma cells without any effect on the phosphorylation of p38, ERK, and JNK." (PMID 34671398, 2021). "In an osteosarcoma in vitro and in vivo models, ATRA inhibited osteosarcoma metastasis via inhibiting M2 polarization of TAMs independent of STAT3/6 or C/EBPβ signaling, thus proposing ATRA as an anti-metastatic potential treatment in osteosarcoma patients." (PMID 32509781, 2020). "In our previous work, we found that several canine and human osteosarcoma (OSA) cell lines, but not normal osteoblasts, exhibit constitutive phosphorylation of STAT3." (PMID 21443800, 2011).
psoriasis (311 papers, 2009 to 2026). An autoimmune condition characterized by red, well-delineated plaques with silvery scales that are usually on the extensor surfaces and scalp. "STAT3 signaling pathways play a key role in psoriasis associated immune cells (especially Th17 cells) as well as in psoriatic keratinocytes." (PMID 40678130, 2025). "We mimicked genetic predisposition of psoriasis patients with STAT3 overexpression in Ker-CT keratinocytes and reproduced a pre-psoriatic like phenotype of non-lesional skin." (PMID 40678130, 2025). "This protein encourages the growth of keratinocytes and triggers an inflammatory reaction via the ERK1/2 and STAT3 signaling pathways, resulting in pathological alterations linked to psoriasis." (PMID 40343299, 2025). "To establish a human-based preclinical in vitro model for treatment development in psoriasis, we sought to generate an immunocompetent 3D model with a defined genetic modification predisposing to psoriasis, namely STAT3 overexpression." (PMID 40678130, 2025). "Variations in the STAT3 gene are associated with increased susceptibility to autoimmune diseases such as psoriasis and multiple sclerosis." (PMID 40601671, 2025). "To investigate the mechanisms by which PSVII mitigates psoriasis-associated inflammation, we examined its effects on the STAT3/NFκB signaling pathway." (PMID 40405066, 2025). "In an in vitro study, CDC6 expression was found to be elevated in psoriatic epidermal cells and inducible by IL-22/STAT3 signaling, a pathway strongly associated with psoriasis pathogenesis." (PMID 39576422, 2025). "More than 60 risk loci have been identified in psoriasis patients, including signal transducer and activator of transcription 3 (STAT3)." (PMID 40678130, 2025). "In this study, we sought to elucidate the mechanisms underlying persistent STAT3 activation in psoriasis, with a focus on the potential role of sphingolipid signaling pathways." (PMID 39833165, 2025). "In summary, this study demonstrated that OMT inhibits Malassezia biofilm formation and ameliorates Malassezia-associated psoriasis by modulating oxidative stress, inflammation, and apoptosis via STAT3/Nf-κB and AhR/Nrf2 pathways." (PMID 41878517, 2025). "Dysregulated or excessive STAT3 signaling has been associated with the onset and progression of various autoimmune diseases, including psoriasis and systemic lupus erythematosus (SLE)." (PMID 40166646, 2025). "The STAT3/NFκB signaling pathway plays a critical role in the inflammatory responses associated with psoriasis." (PMID 40405066, 2025). "Key active compounds, such as piperine, piperlongumine, α-humulene, schizandrin A, schizandrin II, and torilin, were prioritized for their ability to target psoriasis-associated proteins, including STAT3, TNF, IL-6, and NF-κB." (PMID 39590306, 2024). "Activation of Stat3, Erk, and Akt, signaling pathways implicated in psoriasis and indicative of KC proliferation, was detected in K14/Gpx4 epidermis." (PMID 39570671, 2024). "Here, we demonstrated that Rutin mitigated psoriasis‐associated inflammation by inactivating the JAK2/STAT3 signaling." (PMID 39167035, 2024). "The JAK2/STAT3 pathway is a crucial mechanism for intracellular signal transduction and is closely linked to various itching-related diseases, such as psoriasis, specific dermatitis, and nodular prurigo." (PMID 39606625, 2024). "Our findings demonstrated that compared to treatment with deucravacitinib alone, Deu@PEPS is more effective in ameliorating the induction of multiple cytokines and important molecular features associated with psoriasis by STAT3-Krt17-Cyclin D1 pathway." (PMID 38799436, 2024). "Mutations in genes coding for Tyk2, Jak2, and STAT3 have been found to be associated with psoriasis." (PMID 37628670, 2023). "The primary cause of psoriasis is excessive keratinocyte proliferation; STAT3 can promote both cell growth and differentiation." (PMID 36980194, 2023).
psoriasis (continued). "The upregulation and activation of STAT3 has known associations with psoriasis, however, understanding of its expression and role in rosacea remains limited." (PMID 38193038, 2023). "Their proliferation is responsible for the phenotypic outcome of psoriasis and is associated with the IL-22 and IL-6/STAT3 pathways." (PMID 37958980, 2023). "The STAT3 gene, which plays a critical role in psoriasis pathogenesis, is essentially activated by high-risk HPVs in both differentiated and undifferentiated keratinocytes." (PMID 36458289, 2022). "The aberrant STAT3 activation in mouse skin keratinocytes has been linked to psoriasis-like skin inflammation." (PMID 35351863, 2022). "To further prove how triptolide regulates STAT3, we focused on miRNAs which were associated with psoriasis or triptolide." (PMID 36474621, 2022). "In this study, ADE treatment reduced the phosphorylation of JAK2/STAT3 signaling molecules in HaCaT cells and downregulated the mRNA expression of psoriasis hallmark genes." (PMID 36501124, 2022). "The activation of STAT3 is associated with pathologies such as autoinflammatory or autoimmune conditions including psoriasis." (PMID 36474621, 2022). "STAT3 plays an important role in inflammatory responses, and is implicated in the pathogenesis of psoriasis." (PMID 35874668, 2022). "The miRNAs exert their functions through regulating key psoriasis-associated transcription factors including NF-κB and STAT3." (PMID 33718413, 2021). "The Akt/mTOR activation and STAT3 signaling are known to promote acanthosis, which is implicated in the immunopathogenesis of psoriasis." (PMID 33849555, 2021). "The PI3K/AKT/mTOR activation and STAT3 signaling are known to promote acanthosis, which is implicated in the immunopathogenesis of psoriasis." (PMID 34834106, 2021). "The STAT1, STAT3 and NF-κB are known to play a key role of the transcriptome network implicated in the psoriasis development." (PMID 34834106, 2021). "STAT3 is included as one of the genetic risk loci in psoriasis, and was reported as an up-regulated gene in a study of psoriatic patients compared to healthy controls." (PMID 34679602, 2021). "The keratinocyte proliferation in psoriasis is in close association with the signal transducer and activator of transcription 3 (STAT3) pathway." (PMID 34054833, 2021). "This work points to a crucial role of STAT3 in PsA pathogenesis, building upon an extensive literature showing the importance of STAT3 in psoriasis and PsA, including a STAT3 polymorphism (STAT3 rs744166∗G allele) that has been found to be associated with PsA." (PMID 35087513, 2021). "Not only did they reduce psoriasis-associated gene expression, but also inhibited pro-inflammatory pathways such as NF-κB and STAT3 signaling, eventually resulting in reduced cytokine secretion." (PMID 34641358, 2021). "Recently, it has been reported that oxidative stress caused by reactive oxygen species also promotes psoriasis through activation of STAT3." (PMID 34679602, 2021). "K17 expression expressed aberrantly in the suprabasal keratinocytes, which is regarded as a hallmark of psoriasis that is primarily induced by IL-17A through STAT3 and ERK1/2, thus promoting the proliferation of keratinocytes and T cells." (PMID 31924750, 2020). "STAT3 has also been detected in psoriasis GWAS, and its variants are associated with psoriasis risk." (PMID 30909615, 2019). "IL-21 levels in the skin are associated to psoriasis severity, and this cytokine acts on keratinocytes by inducing proliferation and epidermal hyperplasia signalling via STAT3." (PMID 29316631, 2018). "The STAT3 pathway has been widely associated withproliferation and is markedly active in psoriasis patients, likely leading to anincreased IL-17 expression.Persistent activation of STAT3 leads to increased Th17 and keratinocyteproliferation." (PMID 29630472, 2018).